CNN1 (calponin 1)
Diseases named in the same sentence as CNN1 in open-access papers (continued):
Sharing a sentence is not in itself a finding about the gene and the disease.
tumor (continued). "CNN1 (log2FC = −3.885), ARHGAP20 (log2FC = −3.312), and MEG3 (log2FC = −2.612) were downregulated, whereas miR-330 (log2FC = 0.431) was upregulated in tumor samples compared to normal samples." (PMID 38240701, 2024). "The results revealed that SPP1, COMP, THBS2, SERPINE1, and COL11A1 were highly expressed in tumor tissues, while MYH11, TAGLN, and CNN1 were lowly expressed." (PMID 36999888, 2023). "Recombinant TGF-β1 or tumour cell conditioned medium (TCM) elevated α-SMA, calponin 1 and collagen 1 A1 (COL1A1) amount on mRNA and protein level in MSC." (PMID 31409840, 2019). "Primary MSC isolated from human bone marrow were differentiated by TGF-β1 and tumour-cell conditioned medium to myofibroblasts with induced expression of the differentiation markers α-SMA, calponin 1 and COL1A1." (PMID 31409840, 2019). "We speculate that the synergistic effect of CNN1 and VEGF accelerates the formation of the tumor microenvironment, which in turn influences their expressions." (PMID 37153789, 2023). "Interestingly, metastatic PCa samples expressed significantly lower levels of CNN1 and ACTA2 compared with primary tumor samples and normal." (PMID 27935821, 2017). "We speculated that MYL9 and CNN1 may act as tumor suppressor genes in human bodies, however, with the development and progression of CRC, the two hub genes may be captured by tumor cells and turned to be harmful genes, therefore protecting tumor cells becomes the major role of MYL9 and CNN1." (PMID 32127961, 2020). "We therefore hypothesized that the phosphorylation of MYL9 or CNN1 is the key of cell migration process on solid substrates in tumor microenvironment but not in the normal stroma microenvironment, leading to the aggressive progression of CRC." (PMID 32127961, 2020). "This study shows for the first time that CNN1 also plays a critical tumor suppressor role in the non-mesenchymal carcinoma, involving the early event of metastasis of HGSC from the fallopian tube epithelium by maintaining the epithelial architecture and survival within." (PMID 28977852, 2017). "Interestingly, Acta2 and Cnn1 were decreased by 21- and 12-fold, respectively, in stromal Gli1-expressing tumor cells compared with WT, and VIM was not significantly altered." (PMID 27935821, 2017). "We found that CNN1 was indeed positively correlated with normal tissue, early GC expression downregulated gene sets, and the early GC and advanced GC expression upregulated gene sets, which is consistent with our description of its non-linear expression throughout tumor progression." (PMID 37153789, 2023). "Likewise, when we explored the effects of IL1β-silenced tumor cells on co-cultured NCFs, we could observe that cocultured fibroblasts lost the expression of inflammatory cytokines, as IL6, LIF or CCL2, while acquired markers of myofibroblasts (ACTA2, PDPN, MYH11, or CNN1)." (PMID 34066976, 2021).
cancer (21 papers, 2007 to 2025). A tumor composed of atypical neoplastic, often pleomorphic cells that invade other tissues. "CNN1 deficiency causes structural fragility of blood vessels and the peritoneum and promotes hematogenous metastasis and peritoneal dissemination of malignant tumor cells." (PMID 37153789, 2023). "Downregulation of CNN1 leads to a loss of membrane integrity in smooth muscle, the uterus and peritoneum, causing blood vessels to become leaky and allowing cancer cell intravasation." (PMID 35842572, 2022). "Significant differences were observed in the protein concentration levels of S100P, PIGR, C1QBP, TAGLN, and CNN1 between cancer and inflammatory lesions (P ═ 0.0006, P ═ 0.0032, P ═ 0.0008, P < 0.0001, P ═ 0.0094, respectively)." (PMID 39284282, 2024). "In this study, we found that the expression of CNN1 was higher in normal tissue than in pan-cancer tissues, yet this expression would rebound during the progression of cancers." (PMID 37153789, 2023). "Although we made some exploration of the prognostic role, immunotherapeutic potential, and possible mechanisms of action of CNN1 from a pan-cancer perspective using multiple databases and multiple analytical tools, there were still some limitations." (PMID 37153789, 2023). "In this pan-cancer research on CNN1, first, we investigated the expression of CNN1 in various tumors by utilizing databases such as TIMER, CPTAC, and GEPIA." (PMID 37153789, 2023). "This rebounding expression of CNN1 would regulate angiogenesis and the immune checkpoint to contribute to cancer progression and poor prognosis." (PMID 37153789, 2023). "In this study, we conducted a comprehensive pan-cancer analysis to summarize the prognostic significance of CNN1 in various types of cancer." (PMID 37153789, 2023). "Our results showed that the expression of CNN1 was reduced in the pan-cancer tissues, but it was inversed in the CHOL or LIHC." (PMID 37153789, 2023). "When AUC is >0.7, CNN1 is good enough to distinguish cancer cells from the other four types of cells." (PMID 35273914, 2022). "In conclusion, the present paper discovered that CNN1 functions as a cancer repressor gene that inhibits BC cell proliferation and migration and represses glycolysis by regulating HIF-1α pathway." (PMID 35903683, 2022). "In vitro CNN1 was a cancer inhibitor gene that serves as an indicator of liver cancer cell migration." (PMID 35903683, 2022). "In a traditional epithelial carcinoma cell line A1847, CNN1 was less expressed in the more invasive subline A1847-I4." (PMID 28977852, 2017). "Additionally, we explored the impact of CNN1 on mediating angiogenesis, immune checkpoint modulation, and prognostic value to assess its potential applications in targeted cancer intervention." (PMID 37153789, 2023). "In addition, the expression of CNN1 in the advanced stage of pan-cancer tissues was higher than that in the early stage, though it was reversed in BRCA cancer." (PMID 37153789, 2023). "Despite this, CNN1 remains unknown in terms of its effects and mechanisms on angiogenesis, prognosis, and immunology in cancer." (PMID 37153789, 2023). "Nevertheless, the effect of CNN1 involving the initiation and progression of cancers remains largely unknown." (PMID 37153789, 2023). "Recently, studies have manifested that CNN1 is concerned with the development of various cancers." (PMID 35903683, 2022). "CNN1 is considered cancer-suppressive, and indeed it is known to be downregulated in cancers." (PMID 35842572, 2022). "As a result, we found that MYL9 and CNN1 may participate in “pathways in cancer”, “calcium signaling pathway” and “focal adhesion”." (PMID 32127961, 2020). "In addition to its expression in smooth muscle cells, calponin 1 can be detected in ME cells, myofibroblasts, and cancer cells." (PMID 31569405, 2019). "Additionally, spindle carcinoma cells expressed high levels of smooth muscle actin (α-SMA) and calponin-1, typical for these type of carcinoma cells." (PMID 28955712, 2017).
cancer (continued). "In addition, fibroblasts (n = 1 068) were identified by COL1A1 and FAP, endothelial cells (n = 2 561) were positive for RAMP2 and CLDN5 expression, smooth muscle cells (n = 1 100) were defined by TAGLN and CNN1, and epithelial/cancer cells (n = 319) were labeled by KRT14 and KRT17." (PMID 40360503, 2025). "Third, this study was focused on CNN1 bioinformatics analysis and clinical sample detection, but it was slightly weak in strength, and we may add in vitro cellular experiments or in vivo animal experiments to investigate the molecular mechanisms of CNN1 in cancer development in more detail." (PMID 37153789, 2023). "In addition, CNN1 has been demonstrated to play a protective role against various cancers." (PMID 35805203, 2022). "For DSS, biomarker candidates for unfavorable prognosis for EC (CNN1) and the key cell development protein ANK2 (MC) have presented oncogenic properties in EOC and other cancers, respectively." (PMID 40778374, 2025). "Significant differences were observed in protein concentration levels between cancer and inflammatory lesions for S100P, PIGR, C1QBP, TAGLN, and CNN1 (P ═ 0.0006, P ═ 0.0032, P ═ 0.0008, P < 0.0001, P ═ 0.0094, respectively) as shown in." (PMID 39284282, 2024). "As expected, most up-regulated proteins are related to cancer genes, with seven of them known to be enhanced in PCa (SYNM, DES, MYH11, TAGLN, CNN1, LMOD1, and PGM5)." (PMID 38052461, 2024). "Gene set enrichment analysis (GSEA) was used to analyze the expression pattern and bio-progression of CNN1 and the vascular endothelium growth factor (VEGF) in cancer." (PMID 37153789, 2023). "Additionally, we also consider that the expressions of MYL9 and CNN1 are downregulated in CRC because of the general dedifferentiation of cancer cells, but those cancer cells with higher expression of MYL9 and CNN1 may be better suited for migration and metastasis compared with lower expressed ones." (PMID 32127961, 2020). "ACTG2, EZR, CNN1, DES, MS4A12 and NTN1 are all expressed at significantly higher levels in normal tissue compared to adenomatous polyp or carcinoma tissues." (PMID 25423035, 2014). "For example, Calponin gene CNN1, TAGLN, and TMP2 are co-expressed in different cancers." (PMID 34261540, 2021). "Therefore, it is likely that that Frondoside A inhibits the proliferation and metastasis of cancer cells by down-regulating CDK1, CDC20, TOP2A and up-regulating CNN1.It should be noted that the free binding energy between Frondoside A and CDK1 was the lowest, measuring -10.7 kcal/mol." (PMID 38144520, 2023).
infection (1 paper, 2016). The state of being infected such as from the introduction of a foreign agent such as serum, vaccine, antigenic substance or organism. "The genes significantly impacted by infection only in CS included mast cell proteinase-3, γ-glutamyltransferase 5 (GGT5), CD163 as well as those involved in smooth muscle contraction, such as tropomyosin (TPM2), myosin, light chain 9, regulatory (MYL9), and calponin 1, basic, smooth muscle (CNN1)." (PMID 27197554, 2016).
renal diseases (1 paper, 2022). "However, the specific mechanism of the role of CNN1 and PCNT in renal diseases is not well understood and still to be revealed." (PMID 36704339, 2022).
CNN1 also shares sentences with these, for which no sentence is quoted: endotoxemia (2 papers); bronchial hyperreactivity (1); cervical cancer (1); cervical squamous cell carcinoma (1); Dysmenorrhea (1); esophageal adenocarcinoma (1); fibrosis (1); inflammation (1); invasive ductal carcinoma (1); invasive lobular carcinoma (1); liver cancer (1); lung adenocarcinoma (1); Megacystis (1); neuroblastoma (1); non-small cell lung carcinoma (1); pheochromocytoma (1); rectum adenocarcinoma (1); serous ovarian carcinoma (1); thyroid carcinoma (1); triple-negative breast carcinoma (1).